ERBB3 (erb-b2 receptor tyrosine kinase 3)
Diseases named in the same sentence as ERBB3 in open-access papers (continued):
Sharing a sentence is not in itself a finding about the gene and the disease.
breast cancer (continued). "The analysis of a dataset of breast cancer patients unveiled that higher ERBB3 mRNA expression correlates with shorter relapse-free survival in basal-like breast cancers, despite low ERBB3 expression in this breast cancer subtype." (PMID 35406375, 2022). "In detail, luminal A and B breast cancer patients displayed the highest ERBB3 mRNA levels, HER2-enriched and normal-like breast cancer patients showed intermediate levels and basal-like breast cancer patients exhibited the lowest levels." (PMID 35406375, 2022). "Our clinical data showed a correlation between higher ERBB3 mRNA expression levels and shorter relapse-free survival in basal-like breast cancer patients." (PMID 35406375, 2022). "ERBB3 is a typical oncogenic RTK that is upregulated in breast cancer and is directly involved in the development of resistance to both tamoxifen and fulvestrant." (PMID 36142451, 2022). "We suggest that the NRG1/ERBB3/ERBB2 pathway promotes the anchorage-independent growth of basal-like breast cancer cells." (PMID 35406375, 2022). "Our results pave the way towards the development of novel anticancer strategies for basal-like breast cancer patients based on the interception of the NRG1/ERBB3/ERBB2 signaling axis." (PMID 35406375, 2022). "ErbB3 silencing efficacy of newly generated Ad was investigated in various breast cancer cell lines." (PMID 35806132, 2022). "To evaluate a potential role for ERBB3 in basal-like breast cancer cell aggressiveness, we decided to perform in vitro experiments upon activation of this receptor." (PMID 35406375, 2022). "The expression of CircEPSTI1, microRNA miR-145, and ERBB3 in HER2-positive breast cancer cells was evaluated by qRT-PCR and western blot assays." (PMID 36059813, 2022). "Basal-like cell lines, in particular within the basal B subgroup, showed lower ERBB3 mRNA levels compared to luminal cell lines, mirroring the observation in basal-like breast cancer patients." (PMID 35406375, 2022). "In this study, we have elucidated the ability of circRNA as a miRNA sponge to promote the proliferation, migration, and invasion of HER2-positive breast cancer cells via targeting ERBB3." (PMID 36059813, 2022). "Of note, although ERBB3 role in breast cancer progression is well established, our work suggests its specific involvement in basal-like/triple-negative breast cancer cells." (PMID 35406375, 2022). "ErbB receptors are overexpressed in most solid neoplasms in humans, with 50–70% of lung, colon or breast carcinomas found to overexpress ErbB1 or ErbB3." (PMID 35954497, 2022). "In these experiments, the aptamer against ErbB3 was the targeting agent for breast cancer cells, and the siRNA was directed to oncogene survivin." (PMID 34198550, 2021). "We stratified 59 breast cancer cell lines based on ERBB3 or ERBB2 expression by mining the publicly available Cancer Cell Line Encyclopedia (CCLE) database." (PMID 33420373, 2021). "For example, miR-148a has been documented to function as a tumor suppressor in pancreatic cancer, gastric cancer, and breast cancer through targeting ErbB3, STAT3, and CCK-BR, respectively." (PMID 34836544, 2021). "NRDP1 is an E3 ubiquitin ligase that has been shown by our group and others to target ErbB3 for proteasomal degradation in prostate and breast cancer cells and thereby decrease the likelihood cancer progression." (PMID 34503235, 2021). "Particles generated by mixing aptamer-Protamine-siRNA were smaller than 100 nm in diameter and were proven to have high affinity and specificity to target breast cancer cells expressing ErbB3 (HER3)." (PMID 34198550, 2021). "Amplification of ERBB3 had been reported in numerous cancers, including ovarian cancer, gastric cancer, breast cancer, and melanoma, and was correlated with cancer progression and poor prognosis." (PMID 35174063, 2021).
breast cancer (continued). "ErbB3 was frequently upregulated in various of human cancers, including cervical cancer 41, breast cancer 14, gastric cancer 42, colorectal Cancer 43 and ovarian cancer." (PMID 34400880, 2021). "As a suppressor, ectopic expression of miR-205 inhibits cell anchorage-independent growth and proliferation by repressing expression of ErbB3, which is a component of the most potent oncogenic complex ErbB2/ErbB3 heterodimer in breast cancer." (PMID 33413418, 2021). "ErbB3 was upregulated in various cancers, such as breast cancer, gastric cancer, ovarian cancer, prostate cancer, bladder cancer, colon cancer, neck squamous cell carcinoma and melanoma 14-24." (PMID 34400880, 2021). "Its role as a regulator of ErbB3 makes EBP1 a contributor to breast cancer progression and treatment resistance, as it controls, for example, the ErbB2 protein levels and tamoxifen sensitivity in breast cancer cells." (PMID 34948097, 2021). "Up-regulation of BCAR4 (the CA153 susceptibility gene) in the human breast cancer ZR-75-1 cell line promotes the phosphorylation of ERBB2 and ERBB3, enhances the estrogen-dependent effect of tumor cells, and stimulates the proliferation of tumor cells." (PMID 34630106, 2021). "The presented data demonstrate efficient ErbB3 targeting by the single-domain antibody in breast cancer cell cultures, and visualize the existence of isolated clusters of “oncogenic units”, where signaling through ErbB2/ErbB3 heterodimers does occur." (PMID 34572289, 2021). "Overexpression (Ectopic) of miR-205 in breast cancer cells explained the anti-growth properties of this miRNA as noticed by reduced proliferation and clonogenicity via inhibited ERBB3 which was found to be upregulated in these cells." (PMID 32854238, 2020). "For example, in breast cancer, miR-205 was shown to suppress cell growth via directly binding to ErbB3 and VEGF-A." (PMID 32190742, 2020). "For example, miR-143 and miR-145 gain-of-function synergistically suppress cell proliferation and invasion in breast cancer through the repression of ERBB3 protein expression." (PMID 31820783, 2020). "Suppression of ErbB2 breast tumors by MEDICA in ErbB2/neu mouse transgenes as well as in human ErbB2 breast cancer cells was accompanied by loss of plasma membrane ErbB2, together with other ErbB family members, including EGFR (ErbB1) and ErbB3." (PMID 32695336, 2020). "Mucin 1 and ERBB3 were identified as the targets of miR-145 which inhibits migration and proliferation in breast cancer cells." (PMID 32756009, 2020). "We previously showed that SNDX-275, a class I-selective HDACi, induced apoptosis in ErbB2-overexpressing breast cancer cells via down-regulation of both ErbB2 and ErbB3." (PMID 30961642, 2019). "In breast cancer, high level of expression of miR-125b has been shown to cause down-regulation of ERBB2 (HER2) and ERBB3 (HER3), and thereby suppression of tumor growth." (PMID 31360737, 2019). "In human breast cancer, ErbB3 interacts with ErbB2 and thereby generates a potent oncogenic dimer that causes tumor progression." (PMID 30621788, 2019). "Antibody-mediated inhibition of this ERBB2/ERBB3/PI3K axis has been a cornerstone of treatment for ERBB2-amplified breast cancer patients for two decades." (PMID 30898150, 2019). "We now demonstrate that inactivation of ERBB3/PI3K by these therapeutic antibodies is insufficient to inhibit the growth of ERBB2-amplified breast cancer cells." (PMID 30898150, 2019). "Compared with other molecular subtypes, luminal A/B breast cancer, which has a relatively favorable prognosis, exhibits higher ERBB3 expression." (PMID 29731976, 2018).
breast cancer (continued). "In our system, macrophages were the primary cells showing expression of ErbB3, and a blocking antibody against ErbB3 resulted in a significant decrease in macrophage-induced transendothelial migration of breast cancer cells." (PMID 29636067, 2018). "Studies characterizing macrophages co-invading with breast cancer cells showed higher expression of ErbB3, a member of the epidermal growth factor receptor (EGFR) family, in the invasive macrophages." (PMID 29636067, 2018). "Human epidermal growth factor receptor HER3 (ErbB3), a cell membrane-associated protein encoded by the ERBB3 gene, is a promising target for cancer therapy, especially in HER2-positive (carrying ERBB2/HER2 gene amplification) breast carcinoma." (PMID 30367623, 2018). "In another study the inhibitory effect of EGCG on ErbB2 and ErbB3 overexpressing breast cancer cells was evaluated." (PMID 28286519, 2017). "While ERBB3 can potentially dimerize with all members of the ERBB family, several lines of evidence show that the strongest dimer to activate survival pathways like AKT in breast cancer is the ERBB3/ERBB2 dimer." (PMID 28060735, 2017). "Previously, it was reported that ErbB2 and IGF1R can heterotrimerize with ErbB3 to enhance receptor activation and downstream signaling responses in ErbB2-overexpressing breast cancer cells." (PMID 28947975, 2017). "In our own hands, in vitro stimulation of MCF-7Ca ER+ breast cancer cells with HRG led to rapid phosphorylation of ErbB3 and Akt, as well as phosphorylation of ER on Ser167 and Ser305." (PMID 28725482, 2017). "For example, miR-125a, miR-125b, and miR-205 have been reported to functionally cooperate to downregulate the erbB receptor tyrosine kinase family components erbB2/erbB3 in breast cancer cells." (PMID 29312571, 2017). "Here we report that the lncRNA LINC00052 expression correlates positively with HER3/ErbB3 levels in breast cancer cells." (PMID 28036286, 2017). "HER2 has no recognized ligands and heterodimers between HER2 and EGFR (ErbB1/HER1) or HER2 and ErbB3/HER3 are important in breast cancer." (PMID 28369073, 2017). "While high levels of HER2 in cancer cells can give rise to homodimers that activate signaling, heterodimers between HER2 and EGFR (ErbB1/HER1) or HER2 and ErbB3/HER3 appear to be particularly important in breast cancer." (PMID 28369073, 2017). "ERBB3 isoforms have also been expressed intracellularly in breast cancer cell lines as well as in the nucleus of Schwann cells, prostate and breast." (PMID 28591206, 2017). "In particular, amplification and overexpression of ErbB2 and ErbB3 have been correlated to poor prognosis for breast cancer patients." (PMID 27029001, 2016). "Our data indicate the existence of a multiprotein complex consisting of ERM proteins, Ebp50, Hsp90, ErbB2 and ErbB3 in breast cancer cells." (PMID 27029001, 2016). "Recent studies show the significant role of both ErbB3 and ErbB4 as alternative targets for the treatment of breast cancer patients suggesting a pan-ErbB inhibitor strategy that is able to interfere the cross-talk between the various ErbB receptors." (PMID 27832067, 2016). "Our recent studies identified the class I HDAC inhibitor entinostat (SNDX-275 or MS-275) as a special agent to selectively inhibit erbB3 leading to a dramatic reduction of P-Akt in erbB2-positive breast cancer cells." (PMID 26621843, 2016). "In ERα-positive T47-D and MCF-7 human breast cancer cells, overexpression of ERβ not only attenuated Akt signaling via down-regulation of ErbB2/ErbB3 but also improved the sensitivity of these cancer cells to tamoxifen." (PMID 27669218, 2016). "Ligand binding to ErbB3 in SKBR3 breast cancer cell membranes leads to formation of large ErbB3 clusters with modest levels of co-localized ErbB2; this indicates that domain reorganization can occur during signaling." (PMID 27570763, 2016). "The expression of ErbB3 was directly correlated with the degree of sensitivity of breast cancer cell lines to lapatinib." (PMID 26595522, 2016).
breast cancer (continued). "We showed that overexpression of erbB3 upregulated Survivin to confer paclitaxel resistance in erbB2-overexpressing breast cancer cells." (PMID 27177222, 2016). "In breast cancer models, we found an increased requirement for ERBB3 and PIK3CA, members of the ERBB2 and PI3-kinase signaling pathways that are frequently dysregulated in this cancer histology." (PMID 26947069, 2016). "In breast cancer cells, ErbB2, an orphan receptor, is frequently overexpressed and forms a heterodimer with a kinase dead counterpart receptor, ErbB3." (PMID 27531070, 2016). "A recent study showed that miR-143 and miR-145 synergistically inhibit ERBB3 expression in breast cancer." (PMID 26460960, 2015). "In ERBB2-overexpressing breast cancer cells, beta-catenin co-activates AR to drive transcription of several tumor-promoting targets, including ERBB3 {{}}." (PMID 26509276, 2015). "For instance, miR-206 expression was higher in ERalpha-negative MB-MDA-231 cells than in ERalpha-positive MCF-7 cells, and enforced expression of miR-125a or miR-125b led to coordinate suppression of ERBB2 and ERBB3 in the human breast cancer cell line SKBR3." (PMID 26400441, 2015). "Despite its ligand-independent active conformation, ErbB2-induced transformation of breast cancer cells is dependent on ErbB3." (PMID 25630670, 2015). "Breast cancer cells were shown to upregulate ErbB3 via multiple mechanisms to escape pharmacological EGFR inhibition, and in lung cancer cells, autocrine activation of ErbB3 caused resistance to the EGFR-specific small molecule inhibitor Gefitinib." (PMID 25630670, 2015). "For instance, some of the genes enriched in canine iUC samples i.e., PPARG, TBX2, ERBB2, ERBB3 are genes indicative of luminal subtypes of breast cancer in humans." (PMID 26352142, 2015). "Substantial evidence suggests that deregulated ErbB3 expression also contributes to the transformed phenotype of breast cancer cells." (PMID 25630670, 2015). "Our recent studies using both mouse and human mammary/breast cancer cell models indicate that the existence of erbB3 is required to maintain erbB2’s tyrosine kinase activity." (PMID 24886126, 2014). "The correlation between miR-143/145 and ERBB3 was further examined by evaluating ERBB3 expression in the human breast cancer cell line MCF-7 and MBA-MD-231 after overexpression or knockdown of miR-143/145." (PMID 25248370, 2014). "miRNAs are therefore likely to play a biologically relevant role in regulating ERBB3 expression in breast cancer." (PMID 25248370, 2014). "In contrast, co-expression of erbB2 and erbB3 is a common event in breast cancers and breast cancer-derived cell lines." (PMID 24886126, 2014). "In this study, co-treatment with miR-143 and miR-145 showed a synergistic anti-tumor effect both in vitro and in vivo through the negative regulation of ERBB3 in human breast cancer." (PMID 25248370, 2014). "ERBB3, one of the four members of the ErbB family of receptor tyrosine kinases, plays an important role in breast cancer etiology and progression." (PMID 25248370, 2014). "ErbB3 serves as a critical co-receptor of erbB2, and its expression is a rate-limiting factor for erbB2-induced breast cancer cell survival and proliferation." (PMID 24886126, 2014). "The genetic and pharmacological inhibition of ERBB3 results in anti-tumorigenic activity in cancer cells, both in vitro and as xenograft, and sensitizes lung cancer cells and breast cancer cells to lapatinib, a dual TKI of EGFR and ERBB2." (PMID 24970817, 2014). "We found that PI-3 K/Akt-dependent upregulation of Survivin played a vital role in erbB3-mediated paclitaxel resistance in erbB2+ breast cancer cells, and specific knockdown of Survivin abrogated the resistance." (PMID 24886126, 2014).
breast cancer (continued). "Amplification and/or overexpression of erbB3 are frequently observed in various malignancies, such as cancers of breast, gastric, ovarian, prostate, and bladder, colorectal carcinoma, squamous cell carcinoma of the head and neck, and melanoma." (PMID 24886126, 2014). "We next analyzed the biological consequences of the miR-143/145-driven repression of ERBB3 expression in breast cancer cells." (PMID 25248370, 2014). "A retrospective clinical study examining a large cohort of tamoxifen treated, ER + breast cancer patients found that the patients with co-expression of erbB2 and erbB3 were significantly more likely to relapse on tamoxifen." (PMID 24886126, 2014). "We demonstrated that the repression of ERBB3 by miR-143/145 suppressed the proliferation and invasion of breast cancer cells, and that miR-143/145 showed an anti-tumor effect by negatively regulating ERBB3 in the xenograft mouse model." (PMID 25248370, 2014). "Overexpression of ErbB1, ErbB2, and ErbB3 in transgenic mouse models contributes to mammary tumor formation." (PMID 25516216, 2014). "In conclusion, our results demonstrated that miR-143/145 directly recognized and bound to the 3’-UTR of the ERBB3 mRNA transcript and synergistically suppressed ERBB3 expression in breast cancer cells." (PMID 25248370, 2014). "This disparity between protein and mRNA in ERBB3 expression in breast cancers strongly suggests that a post-transcriptional mechanism is involved in ERBB3 regulation." (PMID 25248370, 2014). "Taken together, our findings provide the first clues regarding the role of the miR-143/145 cluster as a tumor suppressor in breast cancer through the inhibition of ERBB3 translation." (PMID 25248370, 2014). "We showed that specific knockdown of erbB3 by a siRNA abrogated erbB2-mediated tamoxifen resistance in breast cancer cells via enhanced apoptosis." (PMID 24886126, 2014). "Along with the biological impact of ERBB3 signaling on ERBB2-amplified breast cancer, active ERBB3 is a means of escape from therapeutic suppression by several tyrosine kinase inhibitors." (PMID 25248370, 2014). "Nonetheless, overexpression of erbB3 has been generally considered as a poor prognostic factor in breast cancer patients." (PMID 24886126, 2014). "Some studies show that erbB3 expression significantly reduces the overall survival and disease-free survival of breast cancer patients." (PMID 24886126, 2014). "ERBB3 is frequently overexpressed in breast cancer and tends to function as an oncogenic unit by forming heterodimers with ERBB2." (PMID 25248370, 2014). "One possibility is ERBB3, since recent work has revealed that the ERBB3 ligand heregulin increases mammosphere formation in breast cancer cell lines, which was attenuated by NFκB pathway inhibition." (PMID 25252859, 2014). "Pertuzumab, a humanized monoclonal antibody that also targets the NH2-terminal domain of ErbB2 and blocks the ErbB2 dimerization with ErbB3, is recently also accepted for a treatment of ErbB2 positive breast cancer in combination with chemotherapy." (PMID 24709902, 2014). "HRG is a ligand for ErbB3 and ErbB4 and has also been reported to promote the invasive behavior of breast cancer cells in vitro." (PMID 23937725, 2013). "It has been well-documented that activation of the erbB3 signaling plays a pivotal role in the development of erbB2-overexpressing breast cancer." (PMID 24168763, 2013). "In contrast, co-expression of erbB2 and erbB3 frequently occurs in breast cancers and breast cancer cell lines." (PMID 24168763, 2013). "Experimentally, miR-125-induced down-regulation of ERBB2 and ERBB3 has been uncovered to reduce cell motility and invasiveness of numerous cancers, including breast cancer and endometrial cancer." (PMID 23321005, 2013). "Here, we study the antitumor activity of an anti-erbB3 antibody MM-121/SAR256212 in combination with paclitaxel against erbB2-overexpressing breast cancer." (PMID 24168763, 2013).